CD83 (CD83 molecule)
Diseases named in the same sentence as CD83 in open-access papers (continued):
Sharing a sentence is not in itself a finding about the gene and the disease.
tumor (continued). "The analysis of memory T cells at day 59 in an independent experiment revealed that most of the M2 specific T cells were effector memory (CD83+CD8+IFNγ+CD44+CD62LLO), thus suggesting that a boost in the immune response could further improve tumor protection." (PMID 30764846, 2019). "Anti-CD83 specific antibodies with the ability to deplete CD83+ cells have shown efficacy in the treatment of pre-clinical models of GVHD without significantly affecting viral or tumor specific memory T-cell responses." (PMID 31231400, 2019). "Expression of tryptase, MAC387, CD83, and CD31, which are markers for MCs, macrophages, mature dendritic cells, and vascular endothelial cells, respectively, was determined via immunohistochemistry of resected tumor specimens." (PMID 26530140, 2015). "To validate the role of GDF-15 in tumor progress, we used a GDF-15 polyclonal antibody to block the GDF-15 induced maturation and the result revealed that the antibody abolished the effect of GDF-15 on inhibiting CD83, CD86 and HLA expression on mDCs in vitro." (PMID 24236027, 2013). "In contrast the co-stimulatory receptors (CD80, CD86) and CD83 are not influenced by the tumor, HLA-DR expression is even decreased in many cases and the early activation marker CD25 is only presented by a small subpopulation [unpublished data]." (PMID 21264308, 2011). "Indeed, DCs detected in tumor tissue or local tumor draining lymph nodes (TDLN) of cancer patients display an immature phenotype defined by low expression of CD80, CD86 or CD83, and altered APC function." (PMID 20976125, 2010). "The removal of the tumor had no or very low effect on CD83 levels when measured ∼12 weeks after surgery, as the CD83 expression remained higher on MDCs (median 0.9%) and PDCs (median 1.5%) compared to controls." (PMID 20976171, 2010). "Further analysis revealed that the expression levels of CD103 and CD83 on cDC1 in the Neo-BCV group were significantly higher than in the PBS group, indicating that the DCs in the Neo-BCV group have stronger antigen presentation ability, laying the foundation for an anti-tumor response." (PMID 39852843, 2025). "Conversely, across both IDHmut and IDHWT tumors, expression of the CD83 gene set positively correlated with antitumor gene sets including CD8+ T-cell, central memory CD8+ T-cell, and Th cell gene sets, which was primarily enhanced in IDHmut tumor samples compared with IDHWT tumors." (PMID 39601621, 2024). "Furthermore, we proved the functional importance of co-stimulatory molecules by showing that co-treatment of hRT/lena-treated mice with antibodies blocking CD70, CD83, and CD86 worsened primary and, more prominently, secondary (abscopal) tumor control and diminished overall survival of the mice." (PMID 38646638, 2024). "Notably, they reported a minimal, yet not statistically significant, increase in LCs CD83+ maturation marker expression for longer tumor excision—SLN biopsy intervals." (PMID 38791968, 2024). "An upregulation of CD83 in the dendritic cells might modulate the MHC-II presentation, thus increasing the recruitment of both immature and mature dendritic cells amplifying the immunitary response against the tumor." (PMID 36831458, 2023). "Of note, sample #15A which according to cytology had few intact tumor cells but a high content of mostly degenerative and inflammatory cells including macrophages (which are PD‐L1‐positive) deviated most from the correlation line for multiple markers, for example, CD4, CD5, CD40, and CD83." (PMID 33768639, 2021). "The number of CD83+ DCs was considered a marker of good prognosis, and their density positively correlated with the number of CD4+ or CD8+ T cells, thus, suggesting that higher frequencies of mature tumor-infiltrating DCs favor the activation of tumor-specific immunity." (PMID 34062821, 2021).
tumor (continued). "Furthermore, immature dendritic cells (iDC) responded to mCD40L with enhanced maturation and activation over sCD40L evidenced by higher expression levels of CD83, CD86, HLA-DR and CD54, increased secretion of IL12 and IL10 and higher tumour-antigen (TA) uptake capacity." (PMID 31941968, 2020). "Oncolysis induced by a recombinant poliovirus-rhinovirus chimera exposed the tumor antigens, while DCs co-cultured with the supernatant from the chimera-infected tumor cells exhibited increased expression of type I IFNs, CD40, CD80, and CD83, suggesting that this virus promotes APC maturation." (PMID 33680911, 2020). "Additionally, only MRF/magnet treatment resulted in significant increases in the frequency of mature DCs (CD11c+MHC II+CD83+) in the tumor-DLNs only and not the NDLNs in comparison to mice receiving cryoablation." (PMID 23133545, 2012). "Moreover, we observed that immune‐related and cell adhesion‐related genes such as CD83, HLA‐DRA, JAK3, CEACAM6, and ITGB238, 39, 40, 41 exhibited high H3K27me3 modification in tumour cells, suggesting that their expression may be suppressed by H3K27me3 to facilitate immune escape of tumour cells." (PMID 39210544, 2024). "Furthermore, the expression of all well-established costimulatory molecules, including CD40, CD54, CD80, CD83, CD86, 4-1BB, GITR (glucocorticoid-induced TNFR-related protein), OX40L, and SLAM (signaling lymphocytic activation molecule), was downregulated in DC-tumor fusion cells." (PMID 26605345, 2015). "Moreover flow cytometry analysis performed on DC induced to maturation with cytokine cocktail in the absence of tumor lysate indicates that expression levels of CD83 on mature-non activated-DC (data not shown) are as homogeneus as observed on “new method” lysate activated DC." (PMID 23284979, 2012). "Thus, in 17 of the 24 investigated cases, no CD83+ DCs were identified within the tumour tissue." (PMID 20969772, 2010). "In particular, its overexpression by axillary lymph nodes could prevent lymph node metastases; nevertheless, the authors of this work found a higher number of mature CD83-positive DCs, but not of immature CD1a-positive DCs, in tumour-free sentinel lymph nodes than those containing tumours." (PMID 15756258, 2005). "Interestingly, the DC maturation marker CD83 was significantly more expressed in wt OAd and OAd.TNFa-IL2-treated tumors as well as KO OAd.TNFa.IL2-treated tumors, indicating that virus-induced AIM2-mediated tumor-cell signaling might play a role in DC activation." (PMID 32225009, 2020). "DCs from the non-adherent cell fraction in the DC/tumor electro-fusion products had significant up-regulation of MHC class II as well as CD80, CD86 and CD83." (PMID 24466232, 2014). "The ethanol-treated and untreated tumor cells (PANC/Mock and PANC/TGF-β) showed sustained expression of HLA-ABC, HLA-A2, MUC1, TLR2, and TLR4, but not HLA-DR, CD80, CD86, and CD83 (data not shown)." (PMID 23717436, 2013). "Based on CD83 expression, GM3, but not pSTAT3, appeared to be involved in tumor-induced DC suppression." (PMID 19519895, 2009). "The results showed no detectable expression of CD80, CD83, or CD86 on the surface of γδ T cells from PBMCs of normal donors (control), peripheral-derived γδ T cells, and γδ T cells directly isolated from tumor tissues (defined as tumor tissue-derived γδ T cells)." (PMID 24741609, 2014).
infection (80 papers, 2007 to 2025). The state of being infected such as from the introduction of a foreign agent such as serum, vaccine, antigenic substance or organism. "Within the P2 population, which was minimally present in uninfected neutrophils, infection caused a substantial enhancement of the CD83 positivity in all cells, which were gated as P5 (CD83+/ CD66b+) neutrophils." (PMID 40340446, 2025). "Upon infection with Borrelia burgdorferi, wt B cells display an enhanced pathogen clearance compared to CD83-deficient cells, which was associated with increased IgE serum levels suggesting a shift toward Th2 responses." (PMID 32362900, 2020). "In summary, we demonstrate that NSR infection of monocyte-derived immature DCs results in incomplete maturation, associated with gradual downregulation of CD83." (PMID 26575844, 2015). "They suggested that infection of mDCs leads to a reduction of merely CD83 surface expression most probably caused by shedding of a soluble form of CD83 which in turn might be responsible for the diminished T cell stimulatory capacity." (PMID 28203230, 2017). "Accordingly, in this study, the transdifferentiated neutrophil subset (P2/P5) infected by AG83 exhibited the highest expression of phagocytic marker CD44, further consolidating the role of CD83 in promoting infection." (PMID 40340446, 2025). "In uninfected neutrophils, the median frequency of CD66b+/CD83+ transdifferentiated P3 population was 1.36% (1.00%–1.49%), which, following infection, translated into a substantial increase in CD66b+/CD83+ to 51.05% (49.48%–53.94%), P < 0.05." (PMID 40340446, 2025). "Following ex vivo infection of neutrophils, infection was evident at 2 h and was accompanied by CD83 positivity." (PMID 40340446, 2025). "After infection with the parasite, the expression levels of CD83, CD86, MHC-I, and MHC-II markers on splenic DCs increased." (PMID 38038457, 2024). "As for some DZ signature genes, the LZ biomarker CD83 is downregulated upon infection in ensemble experiments but retained in EBV+ subsets co-expressing BCL2A1 (BFL-1) and other GC LZ hallmarks (CD80, CD86, and MYC)." (PMID 38059622, 2024). "After 24-h infection, the expression levels of CD83 and CD80 on MoDCs-P were found to be significantly lower than those on MoDCs-NP." (PMID 37983293, 2023). "Markers of B cells (Cd19), T cells (Cd3g), and antigen presentation (Cd74 and Cd83) were elevated in aged lungs at day 3 post-infection." (PMID 37852965, 2023). "In vitro infection of isolated human dendritic cells with Y enterocolitica induced maturation, indicated by upregulation of CD83 and CD86, but downregulated MHC II expression and impaired T cell proliferation up to 6 days post-infection." (PMID 36504866, 2022). "The CD83 gene in the immunization group reached the peak at hour 6 (p < 0.05), whereas, in the infection group, it reached a maximum at hour 12 (p < 0.05)." (PMID 36363767, 2022). "Expression of CD83 was slightly upregulated on mDC and M1 macrophages upon infection with SARS-CoV-2 (MOI 0.1)." (PMID 34122407, 2021). "For FoBs, immune activation during the first weeks of infection is marked by the upregulation of the IFNγ inducible gene Socs3 and the spleen light zone B cell activation marker CD83." (PMID 34762705, 2021). "In human mDCs infected with HSV-1, the degradation of cell surface CD83 expression was seen within 6 to 8 hours after infection and was mediated by proteasome-dependent degradation." (PMID 34895058, 2021). "Especially herpesviruses, which are capable of establishing latency upon lytic primary infections, have acquired immune evasion mechanisms targeting CD83." (PMID 32362900, 2020). "Mice constitutively expressing CD83 under MHC I promoter (CD83Tg) showed reduced production of antigen-specific antibody production upon infection with Leishmania major and Trypanosoma cruzi." (PMID 33302987, 2020).
infection (continued). "On the other hand, the peritoneal cells exhibited an increment in CD3+ T cells for both the wild type and CD83 KO mice after infection although the amounts of T cells at 7 and 15 days post-infection were higher in the wild type mice than in the CD83 KO mice." (PMID 33302987, 2020). "CD83 is known to regulate lymphocyte maturation, activation, homeostasis, and antibody response to immunization and infection." (PMID 33302987, 2020). "Infection by different viruses leads to the degradation of membrane CD83 in dendritic cells, interfering with the maturation and immune response of DCs." (PMID 33302987, 2020). "The peritoneal cavity and serum of the wild type mice contained a high titer of IgG within 14 days after infection, whereas the CD83 KO mice had a very low titer of IgG." (PMID 33302987, 2020). "The depletion of both the B-1 and B-2 cells was observed at 5 days post-infection, followed by partial recovery at 7 days in both wild type mice and CD83 KO mice." (PMID 33302987, 2020). "Because CD83 regulates the development and function of various immune cells, it also modulates the immune response during infections." (PMID 33302987, 2020). "In particular, HSV-2 blocks DC maturation, and thus CD83 surface expression, and additionally induces CD83 degradation after infection of mDCs." (PMID 32362900, 2020). "Peritoneal macrophages showed a decreasing trend whereas MHCII and CD83 cells tended to develop an increasing trend along the infection." (PMID 30547823, 2018). "It has previously been reported that HSV-1-induced CD83 degradation after infection of mDCs can be prevented by inhibition of the proteasome." (PMID 28203230, 2017). "The initial upregulation after NSR infection can be explained by the presence of protein and mRNA pools of CD83 in immature DCs that are ready to be mobilized upon stimulation." (PMID 26575844, 2015). "As we already showed that CD83 levels increase in the first 8-12h after infection and then gradually decrease, we first stimulated DCs with NSRmock, LPS+NSR or LPS+NSRmock for 8 h and then added CLBL in two different concentrations." (PMID 26575844, 2015). "We observed that expression of the co-stimulatory molecule CD83 was inhibited early in P. berghei infections, while dendritic cells from B. duttonii infected animals showed a successive rise in CD83 expression as the infection progressed." (PMID 25075973, 2014). "The location of DEC205+ve and CD83+ve cells during the process of germinal centre formation was studied following infection of birds with MDV." (PMID 23326318, 2013). "During the course of an ongoing infection with Leishmania major, B cells are the dominant CD83 positive cell population and surface expression of CD83 on B cells is strictly correlated with the site and the kinetics of infection." (PMID 17710154, 2007). "The increased CD83 expression by endometrial B cells as compared to peripheral blood B cells suggests its modulatory role in the fetal tolerance, especially in the context of infection." (PMID 39328416, 2024). "Infection of MoDCs by PRRSV increases the release of soluble CD83 in particular." (PMID 36992481, 2023). "However, the proportion of HLA-DR- and CD83-positive DCs were found markedly increased following infection." (PMID 35615366, 2022). "Previous studies have shown that CD83 also affects B cell function during infection." (PMID 33302987, 2020). "However, the CD19+ B cells in bone marrow exhibited an incomplete recovery in the CD83 KO mice until 14 days post-infection, suggesting a delay in the restoration process." (PMID 33302987, 2020). "However, the CD4+ T cell number mildly increased after infection in the CD83 KO mice; however, the total number of cells in the CD83 KO mice was still much lower compared to the wild type mice." (PMID 33302987, 2020).
infection (continued). "Interestingly, earlier studies already reported that enforced expression of CD83 on B cells dramatically interferes with their ability to mount efficient antibody-responses against model-antigens as well as against infection with the parasite Leishmania major." (PMID 32362900, 2020). "Interestingly, at the later stages of our infection model, genes essential for correct antigen presentation (CD83, CD40, HLA-DOA) were downregulated exclusively in STM-D23580-infected cells relative to bystander cells." (PMID 30451854, 2018). "CD83 degradation specifically occurs very early after infection supporting the hypothesis that CD83 is involved in mechanisms important for the initiation of antiviral immune responses especially for T cell activation." (PMID 28203230, 2017). "Therefore, mDCs were mock- or HCMV-infected and analyzed for CD83 expression at different time points post-infection using flow cytometry." (PMID 28203230, 2017). "Moreover, upon infection the percentage of CD83+ cells significantly (P ≤ 0.05) decreased in C57BL/6 and BALB/c GM-BM cultures." (PMID 29312229, 2017). "Additionally, immunofluorescence analyses of mock- or HCMV-infected mDCs 16 hpi also showed an overall reduction of CD83 expression levels upon infection." (PMID 28203230, 2017). "Therefore, with respect to these studies showing the functional importance of CD83, it is not surprising that several viruses, especially herpesviruses, target CD83 upon infection of mDCs." (PMID 28203230, 2017). "To investigate whether proteasomal degradation of CD83 explains the decreased surface exposure of this molecule after NSR infection, we used the inhibitor clasto Lactacystin β-lactone (CLBL) to supress cellular proteasomal activity." (PMID 26575844, 2015). "Interestingly, expression of the most prominent marker of DC maturation, CD83, was consistently downregulated at 24 hours post infection." (PMID 26575844, 2015). "However, in another publication, reduced expression levels of mDCs and CD83 seen in SLE patients might contribute to a higher infection prevalence." (PMID 36769151, 2023). "Myeloid DCs and CD83 expression level decrease and may explicate the infection in SLE patients." (PMID 36769151, 2023). "Some of these changes have been observed in sheep, where infection with F. hepatica produced hyperplasia of the hepatic lymph nodes with increased numbers of DC at 18 dpi, but a significant decrease in the expression of their antigen presentation markers (CD83 and MHC-II)." (PMID 34122452, 2021). "Furthermore, VZV also selectively inhibits CD83 expression on mDCs upon infection." (PMID 32362900, 2020). "To evaluate whether the reduced CD83 surface expression observed after NSR infection correlated with reduced mRNA levels, we analysed with qRT-PCR the quantities of CD83 mRNA in DC lysates prepared 24 h post NSR or LPS+NSR stimulation, resulting in more than 90% GFP-positive cells." (PMID 26575844, 2015). "Infection with AG83 enhanced apoptosis in P1 and P2 neutrophil populations, the maximal being in the CD66b+/CD83+ transdifferentiated P2 population." (PMID 40340446, 2025). "Expression of CD83 and CD69 was higher in adults compared to children when analyzing the total number of B cells contained in all infection-induced clusters highlighting the concordance with the CyTOF data." (PMID 40834853, 2025). "Similar to the response to WT STm infection, ΔprgH STm infected 2D enteroids regulated CCL5 and DTX2 at 4 hpi and genes involved in the regulation of antigen presentation (CD83), and inhibition of NFκB activation (NFAIP2)." (PMID 37854334, 2023). "Following Lt-wt infection, DCs expressed significantly higher levels of CD80/CD83 and HLA-DR II compared to MED treatment." (PMID 35632559, 2022). "S. Typhimurium-infected chMoDCs showed significant upregulation in the expression of costimulatory (CD40, CD80, CD83 and CD86) and MHC molecules at 6 h post-infection in comparison to S. Gallinarum." (PMID 34446765, 2021).